SMAD4 (SMAD family member 4)
Diseases named in the same sentence as SMAD4 in open-access papers (continued):
Sharing a sentence is not in itself a finding about the gene and the disease.
tumor (continued). "Next, we evaluated the specific promoter methylation of the four genes from the TGFβ signaling pathway (TGFBR2, SMAD4, SMAD7 and SNAI1) evaluated in SNU449 cells in resected human HCC tumors, as well as in the surrounding non-tumor tissues." (PMID 34571856, 2021). "SMAD4 belongs to the SMAD protein family, which is involved in the TGF-β signaling pathway that usually impedes immune activation in the tumor microenvironment." (PMID 33500720, 2021). "The classical group was enriched in SMAD4 and GATA6, while the basal subtype was molecularly similar to basal tumours in bladder and breast cancer." (PMID 33371431, 2020). "Thus, it may be more effective to use oncolytic viruses to carry the Smad4 gene in tumor therapy." (PMID 33322272, 2020). "The tumor suppressor genes APC and SMAD4 had an inordinately high number of frameshift or nonsense mutations." (PMID 33050525, 2020). "Smad4 is a unique and central transducer of TGF‐β responses and is important for most TGF‐β‐induced biological effects, including tumor metastasis/invasion and embryonic development." (PMID 31721429, 2020). "Collectively, these results demonstrated that MIR22HG exerted its tumor suppressive function through competitively binding to SMAD2, thereby preventing the interaction between SMAD2 and SMAD4 in CRC cells." (PMID 32127004, 2020). "When the tumor suppressor gene SMAD4 is expressed by PDAC cells, S100A8 and S100A9 are produced by the tumor infiltrating inflammatory cells." (PMID 30764482, 2019). "SMAD4 can also regulate the expression of vascular endothelial growth factor (VEGF)-A and VEGF-C, the main angiogenic factors for tumor angiogenesis and lymphangiogenesis." (PMID 31756952, 2019). "It exercises its role as a tumor suppressor by negatively regulating the expression of target genes such as PTEN, TGFBR2, ZBTB4 and SMAD4." (PMID 31200745, 2019). "Upon receptor-regulated phosphorylation by TGF-β, pSMAD2/pSMAD3 forms a complex with SMAD4 and acts as a coactivator of numerous TGF-β target promoters in the nuclei that contributes to either tumorigenesis or tumor progression, depending on the context." (PMID 31640193, 2019).
tumor (continued). "In the early stage of tumor progression, TGF-β acts as a tumor suppressor by inducing apoptosis and inhibiting tumor cell growth, due in part to its activation of the proapoptotic WWOX and Smad4." (PMID 31315632, 2019). "We confirmed that LY reduced tumor growth, inhibited TGF-β/SMAD4 pathway activation and reversed irradiation-induced EMT in a tumor xenograft model." (PMID 31631064, 2019). "PI3K/Akt pathway can activate Snai1 and slug expression that has been correlated with EMT and invasive tumor types through repression of E-cadherin and occludin expression mediated by Snai1/SMAD3/SMAD4 complex." (PMID 31798766, 2019). "Overexpression of miR-146a resulted in decreased expression of SMAD4 together with tumor supportive gene MMP9 in microglia, and subsequently suppressed microglial migration towards GCM, possibly through regulation of SMAD4." (PMID 29861845, 2018). "Recent studies have provided evidence on the prognostic and likely predictive role of SMAD4 and BRAF, two genes that are currently considered tumor suppressors in CRC." (PMID 30282914, 2018). "These more frequently mutated instances encompassed in total 53 genes and included the experimentally characterized hotspots within the PTEN, FBXW7, SMAD4, EP300, and CREBBP tumor suppressors." (PMID 29572294, 2018). "In this study, we show that overexpression of MUC1 in human SMAD4 deleted PDA cell line BxPC3, plays an important role in the switch of TGF-β from a tumor suppressor to a tumor promoter, via a SMAD4 independent mechanism." (PMID 29467938, 2018). "The intrahepatic tumour nodules were then evaluated for expression of E‐cadherin, Vimentin, Snail+Slug, MMP2 and Smad4 by immunohistochemical analysis." (PMID 29148232, 2018). "Microglia treated with GCM showed an induction of tumor promoter gene MMP9, concomitant with an increase in SMAD4 level." (PMID 29861845, 2018). "Other tumor suppressor genes, such as WT1, SMAD4, and BRCA2, which are also silenced in all samples, are frequently associated to polycomb-repressed (E15, H3K27me3) or heterochromatin-like (E12, H3K9me3) states." (PMID 29773832, 2018). "Functional analysis through shRNA-mediated stable knockdown of SMAD4 in microglia revealed the downregulation of the expression of matrix metalloproteinase 9 (MMP9), which has been shown to be involved in tumor progression and cell migration." (PMID 29861845, 2018). "Patients with high expression of USP22 and low expression of Smad4 significantly has lower AFP, smaller tumor size and higher TNM stage." (PMID 28445968, 2017). "Taken together, these studies suggest that in low-expressing SENP1 LNCaP cells, SENP1 over-expression down-regulated SMAD4 protein expression and promoted EMT of tumor cells." (PMID 28417919, 2017). "Smad4 is a critical effector of TGF-β signaling and is involved in cell differentiation, proliferation, and tumor suppression, but its role in the brain is less clear." (PMID 29183317, 2017). "In a non-canonical signaling, TGF-β binds membrane hyaluronidase Hyal-2 for recruiting tumor suppressors WWOX and Smad4, and the resulting Hyal-2/WWOX/Smad4 complex is accumulated in the nucleus to enhance SMAD-promoter dependent transcriptional activity." (PMID 27845895, 2017).
tumor (continued). "These samples are used to confirm immunohistochemistry analysis using reverse transcription quantitative polymerase chain reaction (RT-qPCR) as a second method to analyze CXCR4, SMAD4, SOX9 and IFIT3 mRNA expression of the tumor." (PMID 28356064, 2017). "In a non-canonical pathway, transforming growth factor beta (TGF-β) binds membrane Hyal-2 and then recruits tumor suppressors WWOX and Smad4, and the resulting Hyal-2/WWOX/Smad4 induces SMAD-dependent transcriptional activation in the nucleus." (PMID 27845895, 2017). "Biomarker expression of CXCR4, SMAD4, SOX9 and IFIT3 will be prospectively assessed by immunohistochemistry and verified by rt.-PCR from tumor and adjacent healthy pancreatic tissue of surgical specimen." (PMID 28356064, 2017). "In addition to AKT1 and its substrates, we found a densely connected group of kinases that regulate the mitotic cell cycle in the SMAD4 dependency network, suggesting that SMAD4 mutant tumor cell lines may have an increased sensitivity to perturbation of this process." (PMID 26947069, 2016). "It has been reported that DNA methylation of SMAD4, LEF1, and CCR7 demonstrate varying expression levels (p < 0.05) between tumor and normal samples (MethHC database), which support our results." (PMID 26895224, 2016). "Immunohistochemical staining revealed that Smad4 and LEF1 were expressed in the nuclei of tumor cells." (PMID 27595937, 2016). "RHOA, SMAD2, SMAD4, SMAD5, SMAD6, BMPR1A, SMAD7 and MYC-, which thereby emerge as candidate genes to play an important role in CRC tumor metastasis." (PMID 27662660, 2016). "SMAD4 is a transcription factor that plays a pivotal role in TGF-β signaling, and is one of the tumor suppressors of CRC." (PMID 27136535, 2016). "SMAD4 is one of the important components in the induction of TGF-β signaling and has been reported to be a tumor suppressor." (PMID 27528036, 2016). "Previous reports showed that full-length HBx can transcriptionally suppress a subset of important tumor-related genes through enhancing the promoters binding to transcription suppressors like E2F1, SMAD4, YY1 and MAZ." (PMID 27391153, 2016). "Among these genes, SMAD4 is a co-activator and mediator of signal transduction by TGF-beta and acts as a tumor suppressor." (PMID 27822437, 2016). "However, we could not observe a characteristic accumulation of SMAD4 mutations in a special histological subtype, but mutations were scattered over different tumor types." (PMID 26053092, 2015). "The tumor-specific overexpression of TOB1 results in the activation of other tumor suppressor proteins, such as mothers against decapentaplegic homolog 4 (SMAD4) and phosphatase and tensin homolog-10 (PTEN), and blocks tumor progression." (PMID 26694352, 2015). "In summary, our results have identified miR-34a as a tumor suppressive miRNA in human EHCC, which acts at least in part through the repression of Smad4." (PMID 26077733, 2015). "Smad4, also termed DPC4, is a tumor suppressor gene that is recognized as a common intracellular mediator that can alter transforming growth factor β (TGF-β) signaling to promote tumor progression." (PMID 25333693, 2014). "The transforming growth factor, beta (TGFB) receptor II (TGFBR2) and SMAD4 genes are commonly inactivated in several types of cancer, providing evidence that the TGFB signal functions as a tumor suppressor." (PMID 24886203, 2014). "Although it is assumed that the growth-inhibitory function of TGF-β is important in SMAD4 tumor suppressor activity, data has also suggested a TGF-β independent function of SMAD4, which modulates the interaction of the tumor with the microenvironment." (PMID 24624093, 2014). "We also examined the tumor region of the extracted tissue by ICH with anti-Smad4 polyclonal antibody, and found higher levels of Smad4 expression in the lung tissue extracted from mice in the vector-only control group." (PMID 25424420, 2014).
tumor (continued). "Smad4 plays a pivotal role in regulating TGF-β signaling and can function as a tumor suppressor or promoter." (PMID 24944686, 2014). "We interrogated the tumor biorepository at MD Anderson Cancer Center and examined archival material including DNA, plasma and tumor tissue samples for SNPs, TGF-β1 plasma level and protein expression of TGF-βR2 and SMAD4." (PMID 24465802, 2014). "Activin A inhibited cellular growth in the cell lines with wild-type ACVR1B and SMAD4 genes, and ACVR1B-knockdown enhanced cellular growth and colony formation in vitro as well as tumor growth and tumorigenicity in vivo." (PMID 24886203, 2014). "In tumor cells, SMAD3/SMAD4 mediates transcription of SNAIL and SLUG, two master regulators of the EMT process." (PMID 24756567, 2014). "Thus, SMAD4 tumor suppressor function may also occur through regulation of an angiogenic mechanism." (PMID 24624093, 2014). "Immunoblotting analyses showed that phosphorylated MEK and ERK compared to total ERK, as well as phosphorylated SMAD2/3 compared to total SMAD2/3 and SMAD4, were increased both in SNORD113-1 siRNA transfected HepG2 cells and in HCC tumor tissues." (PMID 25217841, 2014). "The introduction of functional Smad4 into the tumorigenic and metastatic TβR-KRAS line significantly suppresses tumorigenicity and metastasis, which emphasizes a strong tumor suppressive role in PDAC." (PMID 24386371, 2013). "Smad4 restoration re-established TGF-β sensitivity, markedly increased tumor latency by promoting apoptosis, and decreased metastatic potential." (PMID 24386371, 2013). "Smad4, the pivotal transducer of the TGF-β and BMP signaling pathway, acts as an important tumor suppressor." (PMID 23393589, 2013). "Bioinformatic analysis of mRNA targets of the altered miRNAs, identified oncogenes like ERBB2, YY1, several MAP kinases, and known tumor-suppressors like FOXA1 and SMAD4." (PMID 22438871, 2012). "In contrast to the strong Smad4 staining in normal mucosa, Smad4 is reduced or lost in HNSCC and adjacent non-tumor tissues." (PMID 22204491, 2011). "We examined the paired tumor and normal tissue specimens of 86 CRC patients for the occurrence of aberrations in MCR region of SMAD4 and exon 1 of KRAS by PCR-SSCP and/or PCR-Direct sequencing." (PMID 20565773, 2010). "The study concluded that SMAD4 is a PDAC tumor suppressor, functioning to block the progression of KRASG12D-initiated neoplasm's." (PMID 20565773, 2010). "Strikingly, the observed rate of homozygous deletions within LRP1B in human cancer cell lines is equivalent to or higher than known recessive tumor-suppressor genes such as PTEN, RB1 and SMAD4 in the same cell line dataset." (PMID 20942901, 2010). "The SMAD4 gene (also referred as DPC4, for deleted in pancreatic carcinoma locus 4) shares characteristics with typical tumour suppressor genes, including involvement in the transforming growth factor-β signalling." (PMID 19352382, 2009). "The SMAD4 gene is an intracellular mediator of the TGF-β and BMP signal transduction pathways and a tumor suppressor involved in pancreatic and colorectal tumorigenesis." (PMID 19014666, 2008). "It would be interesting to correlate the Smad4 status of the tumour cells with TGF-β and BigH3 levels in this tumour panel." (PMID 17997817, 2007).
tumor (continued). "Loss on 18q included the well known 18q21.1 area which is known to harbour the tumour suppressor genes SMAD2 and SMAD4, which function in the TGFβ-pathway e.g. to mediate the growth-inhibitory effects of this cytokine." (PMID 17407575, 2007). "Smad4 is an intracellular transmitter of TGF-β signals and its tumour suppressor function is presumed to reside in its capacity to mediate TGF-β-induced growth inhibition." (PMID 15785755, 2005). "Tumour suppressor genes such as nm23, DCC and Smad4 have been reported to play a role in liver metastasis." (PMID 12618882, 2003). "Together, these findings reveal a non-canonical role for a transcription factor (e.g., SMAD4) in regulating dysregulated 3D genome architecture to inhibit tumor development." (PMID 42189071, 2026). "In parallel, PTEN loss increases SMAD4 expression and sensitizes the tumor cells to TGFβ signaling, with TGFβ treatment repressing SOX9 expression in tumor cells lacking PTEN." (PMID 41646383, 2026). "Consequently, elevated palmitic acid levels in turn reinforce SMAD4 palmitoylation, establishing a self-amplifying SMAD4 palmitoylation-FASN-palmitic acid positive feedback loop that drives PDAC tumor growth." (PMID 41885390, 2026). "The mechanism linking oncogenesis and the loss of chromosome 18 in these tumors has been investigated, with the hypothesis that the SMAD4 and SMAD2 tumor suppressors played an important role, but the answer is still unclear." (PMID 41416936, 2026). "SMAD4 transcriptionally upregulates GATA6, which amplifies TGF-β signaling by directly activating the TGF-β promoter, establishing a self-reinforcing feedforward loop critical for CAF identity and stromal-tumor crosstalk." (PMID 40216762, 2025). "This transdifferentiation process appears to provide at least one strategy for tumor immunoevasion, mediated by tumor-secreted TGFβ inducing NK signaling via a non-canonical Smad4 independent pathway." (PMID 40873573, 2025). "Future work should include experimental interrogation of SMAD4, BMPR1A, and other TGF-β pathway alterations in preclinical models, as well as advanced approaches such as single-cell sequencing and spatial biology to dissect tumor–microenvironment interactions." (PMID 41009631, 2025). "The SMAD4 protein plays a tumor-suppressive role, and cells lacking this protein avoid cell cycle arrest and apoptosis." (PMID 39361216, 2025). "Knockdown of SMAD4 in UMUC3 (miR-146bi) cells reversed the inhibition of anchorage-independent growth of BCa, indicating the consistent suggestion that SMAD4 may be a tumor suppressor for BCa tumorigenic growth." (PMID 40224178, 2025). "Specifically, recurrent alterations in transforming growth factor beta receptor type 2 (TGFBR2), SMAD family member 2 (SMAD2), and SMAD family member 4 (SMAD4) genes were detected, potentially impairing TGF-β signalling and underscoring the role of immune dysregulation in tumour biology." (PMID 41465261, 2025). "The SMAD4/C-MYC/Cyclin D1 axis plays a pivotal role in regulating key aspects of cancer biology, particularly in the context of cell cycle progression, proliferation, and tumor growth." (PMID 40224178, 2025).